H1-10-AS1 (H1-10 antisense RNA 1)
Synonyms: FLJ34151; formerly C3orf47; H1FX-AS1
Gene: Long non-coding RNA gene on chromosome 3 (129,315,392 to 129,391,296, forward strand). Ensembl gene ENSG00000206417.
Diseases named in the same sentence as H1-10-AS1 in open-access papers:
H1-10-AS1 is named in the same sentence as 1 disease in open-access papers, as found by Europe PMC text mining. Sharing a sentence is not in itself a finding about the gene and the disease.
H1-10-AS1 shares sentences with these, for which no sentence is quoted: tumor (1 paper).